TTR (transthyretin)
Diseases named in the same sentence as TTR in open-access papers (continued):
Sharing a sentence is not in itself a finding about the gene and the disease.
amyloidosis (continued). "To date, over 150 TTR variants have been identified in ATTRv amyloidosis." (PMID 40429804, 2025). "Additionally, we identified interactions between LILRB receptors and transthyretin oligomers, another amyloid linked to transthyretin amyloidosis, suggesting a broader paradigm of amyloid–LILRB interactions." (PMID 41233352, 2025). "Changes in echocardiographic variables were related to all-cause mortality in a landmark analysis using multivariable Cox models adjusting for clinical covariates (age, sex, TTR genotype, atrial fibrillation status, New York Heart Association class and National Amyloidosis Centre stage)." (PMID 41098006, 2025). "Bone scintigraphy, with a detection rate of approximately 13%, can detect both hereditary and ATTRwt amyloidosis but may yield false-negatives with in the presence of certain TTR mutations." (PMID 40574817, 2025). "Additionally, the proportion of different TTR variants in amyloidosis cohorts remains controversial." (PMID 40260709, 2025). "Of 140 identified TTR gene mutations, few are associated with oculoleptomeningeal amyloidosis." (PMID 40681261, 2025). "Acoramidis (formerly AG10) is an orally administered small-molecule drug specifically designed to mimic the protective T119M TTR variant—a naturally occurring mutation that enhances tetramer stability and reduces the risk of amyloidosis even in the presence of pathogenic variants." (PMID 40649158, 2025). "Family history was more prevalent in the amyloidosis group (24.8% vs. 5.4%), consistent with epidemiological data on variant transthyretin (ATTR) amyloidosis, particularly the Val122Ile mutation, which is more commonly seen in African American and Caribbean descendants." (PMID 40943826, 2025). "One of the study’s strengths is the large sample size and the homogeneous ethnicity of the participants, which allows for the assessment of clinical symptoms and the presence of the relevant TTR variants in participants with suspected amyloidosis in an unbiased way." (PMID 39458146, 2024). "CA is primarily caused by either AL or transthyretin (ATTR) amyloidosis." (PMID 39759501, 2024). "Interestingly, previous studies found a correlation between mitochondrial haplogroups and the risk of developing TTR-amyloidosis." (PMID 39615680, 2024). "The aggregation of transthyretin (TTR) results in the formation of amyloid fibrils and it has been reported that monomer unfolding is the underlying cause of life-threatening transthyretin amyloidosis." (PMID 41256008, 2024). "More than 100 TTR point mutations have been reported, and most of them usually lead to a less stable protein than wild‐type TTR and are associated with amyloid diseases (amyloidosismutations.com/mut‐attr.php)." (PMID 39039431, 2024). "Hereditary transthyretin (ATTRv, v for “variant”) amyloidosis is a clinically and genetically heterogeneous, adult-onset, autosomal-dominant disease with variable penetrance, caused by mutations in the gene encoding transthyretin (TTR)." (PMID 37938457, 2024). "Notably, our patient also has a heterozygous V122I TTR variant, predisposing her to ATTRm amyloidosis." (PMID 39736876, 2024). "Since adducts on cysteine 10 also may affect the stability of TTR this has previously been investigated as a potential risk factor regarding TTR-amyloidosis." (PMID 39615680, 2024). "The most common form of hereditary amyloidosis is associated with variants of transthyretin (TTR)." (PMID 38537102, 2024). "ATTR is the term used to refer to amyloidosis caused by misfolding of the TTR protein." (PMID 39540049, 2024). "In individuals with a normal TTR genotype, insoluble amyloid deposits may also accumulate primarily in the heart and cause cardiomyopathy associated with wild type transthyretin amyloidosis (ATTRwt)." (PMID 38410247, 2024).
amyloidosis (continued). "In this article, we summarize the best practices in amyloidosis centers in three major endemic countries for ATTRv amyloidosis (Japan, Brazil, and Portugal), where most patients carry the Val30Met mutation in the transthyretin gene and the patients’ genetic background was proven to be the same." (PMID 37828588, 2023). "Cardiac involvement is usually related to misfolded monoclonal immunoglobulin light chains or misfolded transthyretin; however, apolipoprotein A-1-associated amyloidosis is a hereditary form of amyloidosis resulting from mutations in the AAPOA1 gene that can also result in cardiac amyloidosis." (PMID 38130865, 2023). "In addition to being a carrier, TTR is also widely recognized for its close association with amyloidosis." (PMID 37688511, 2023). "Moreover, transthyretin (TTR) amyloidosis, an autosomal disorder caused by TTR gene mutations, has seen promising results in therapy using CRISPR-based gene editing with NTLA-2001." (PMID 38186450, 2023). "The subpial TTR amyloid deposits were associated with astrocytosis." (PMID 36198883, 2023). "Hereditary transthyretin-mediated (hATTR) amyloidosis, a genetic disease caused by mutations in the transthyretin gene, leads to progressive sensory and autonomic neuropathy and/or cardiomyopathy and is associated with renal and ophthalmologic manifestations and a poor prognosis." (PMID 36829087, 2023). "This literature could serve as a guide for neurologists around the world in choosing the tests and examinations based on their feasibility to best manage TTR gene mutation carriers and patients with ATTRv amyloidosis." (PMID 37828588, 2023). "Amyloidosis is a restrictive infiltrative cardiomyopathy characterized by deposition of amyloidogenic, misfolded insoluble proteins—mostly wild-type or inherited mutated transthyretin (ATTR) and light chains (AL)—in the extracellular matrix between myocytes." (PMID 36676118, 2023). "However, while the V30M TTR variant is responsible for earlier onset of CNS amyloidosis, its amyloid deposits consist mainly of full-length WT-TTR." (PMID 38203650, 2023). "Several studies in patients with ATTRv amyloidosis suggest that the presence of single nucleotide polymorphisms (SNPs) in genes other than the TTR may influence the development of the disease, affecting its age of onset." (PMID 37784196, 2023). "Evaluation of biomarkers is of particular value in patients at higher risk for developing amyloidosis due to the presence of monoclonal gammopathy of unknown significance (MGUS) or TTR gene mutations." (PMID 35929637, 2023). "Hereditary transthyretin amyloidosis variant (ATTRv) caused deposition of variant TTR protein." (PMID 37711552, 2023). "The most frequent forms of CA are light-chain (AL) and transthyretin-related (ATTR) amyloidosis that can be classified in hereditary (ATTRv) or wild-type (ATTRwt) depending on whether a mutation of TTR gene has been identified." (PMID 36970351, 2023). "According to current evidence as follows, Aβ, microtubule-associated protein tau and transthyretin amyloidosis (ATTR) may be the key proteins in bridging CAA and CA." (PMID 36910141, 2023). "We hypothesized that variant TTR derived from the transplanted liver of ATTRv amyloidosis patients might affect the eye." (PMID 37713404, 2023). "Since low TTR expression has no significant side effects, adopting a modality that permanently eliminates the mutated TTR gene may be able to eradicate TTR amyloidosis." (PMID 36646687, 2023). "As demonstrated in the French FAP Network, which consists of a coordinating center in Paris and specialized rare neuromuscular disease centers located across the country, a referral network is crucial for the appropriate management of TTR gene mutation carriers and patients with ATTRv amyloidosis." (PMID 37828588, 2023).
amyloidosis (continued). "Patients with ATTRv amyloidosis were more uniformly spread out among Clusters 2 to 4 as well as Cluster 6, which reflects the variation in phenotypic manifestation (cardiomyopathy and neuropathy) between the various TTR variants and the ages of ATTRv patients." (PMID 36982754, 2023). "Cardiac amyloidosis is primarily associated with aggregates of amyloidogenic proteins, which may be immunoglobulin light chain proteins (AL) or transthyretin proteins (TTR), in many cardiac structures causing different types of amyloidosis." (PMID 36769832, 2023). "Most promisingly, a phase I clinical trial in which genome editing is being used to treat transthyretin amyloidosis with polyneuropathy by targeting the TTR gene (encoding transthyretin, a thyroxine and retinol transport protein) in the liver is already under way." (PMID 34981785, 2022). "Transthyretin (TTR) amyloidosis is associated with tissue deposition of TTR aggregates." (PMID 35724960, 2022). "Meanwhile, the approval of Onpatro (Patisiran), the first small interfering RNA (siRNA)-based drug for the treatment of nerve damage caused by hereditary transthyretin-mediated amyloidosis, raises the prospect of miRNA as a therapeutic agent for genetic diseases." (PMID 35887128, 2022). "A man from Benin was reported with cognitive changes, a sensori-motor neuropathy with autonomic involvement and sensory ataxia, as well as hypertrophic cardiomyopathy, and a TTR I107V variant, which has been found in several Europeans with inherited amyloidosis." (PMID 35331287, 2022). "As in the case of variant transthyretin amyloidosis (ATTRv), partial unfolding or misfolding may easily occur because of a change in the amino acid sequence (genomic single-point mutation) of transthyretin (TTR)." (PMID 35683015, 2022). "The systemic amyloid diseases such as the transthyretin (TTR) amyloidoses and light chain amyloidosis are associated with the deposition of the amyloidogenic proteins TTR or amyloidogenic Ig light chains (LCs), respectively, in tissues distant from their site of synthesis." (PMID 35191945, 2022). "Variant transthyretin amyloid (ATTRv) amyloidosis is a hereditary, life-threatening, and under-recognized disease, in which a misfolded transthyretin (TTR) protein forms amyloid fibrils and deposits in organs and tissues, thereby disrupting normal organ function and tissue structure." (PMID 35893595, 2022). "There are two distinct forms of ATTR amyloidosis: hereditary or variant ATTR amyloidosis (ATTRv amyloidosis), which is caused by pathogenic mutations that destabilize the TTR protein, and wild-type ATTR amyloidosis (ATTRwt amyloidosis), which results from the accumulation of wild-type TTR protein." (PMID 35717381, 2022). "Onpattro® (patisirna) is the first siRNA drug, approved by the FDA in 2018, for the treatment of hereditary amyloidogenic transthyretin (ATTRv) amyloidosis, which is caused by mutation of the transthyretin (TTR) gene and misfolded aggregates of TTR protein in liver." (PMID 36015212, 2022). "This further highlights the potential for enhancing the activity of key ER quality control factors including BiP or PDIA4 through mechanisms such as ATF6 activation to ameliorate pathologic extracellular aggregation of TTR implicated in amyloid disease pathogenesis." (PMID 35626697, 2022). "Indeed, in its wild-type form, TTR can lead to aging-associated amyloid deposition mainly affecting the heart, causing ATTRwt amyloidosis (formerly known as senile cardiac amyloidosis, SCA, or senile systemic amyloidosis, SSA)." (PMID 36555787, 2022). "ATTR cardiac amyloidosis is caused by amyloid originating from transthyretin, which has become unstable due to aging in wild-type (normal) transthyretin amyloidosis (ATTRwt) or due to a genetic transthyretin mutation, leading to a variant transthyretin protein (ATTRv)." (PMID 35892668, 2022). "Transthyretin (TTR) is one of more than 30 amyloidogenic proteins associated with amyloid diseases." (PMID 34343569, 2021).
amyloidosis (continued). "Most patients with ATTRv amyloidosis experience a mixed phenotype with both cardiac and neuropathic symptoms; however, depending on the TTR mutation, patients may experience predominantly cardiac or neuropathic symptoms." (PMID 33957949, 2021). "In addition, we included 14 individuals (9.3%) with known amyloidogenic TTR mutations, of whom 10 were stage 1 ATTRv amyloidosis patients and 4 were asymptomatic carriers." (PMID 34708324, 2021). "According to our data, for the studied TTR variants, vitreous amyloidosis occurs when the combination of the mutated position and the identity of the substituent residue results in a high dynamism and destabilization, which endorses the variant with increased amyloidogenicity." (PMID 34343569, 2021). "TTR amyloidosis can be familial due to a mutation, or a result of older age (wild-type or senile)." (PMID 34524619, 2021). "The phase three trial of revusiran that targets hepatic transthyretin (TTR) for treating cardiomyopathy caused by hereditary transthyretin-mediated (hATTR) amyloidosis was discontinued after a median of 6.71 months due to observed mortality imbalance between revusiran and placebo cohorts." (PMID 33996898, 2021). "The ineffectiveness of diflunisal for amyloidosis treatment trial against the E51-S52 duplication variant of TTR may support this hypothesis." (PMID 33922648, 2021). "In the absence of TTR pathogenic variants, spontaneous dissociation of TTR tetramers may occur (usually later in life), determining ATTRwt amyloidosis (senile amyloidosis)." (PMID 34062949, 2021). "One of the most common causes of CA is transthyretin (TTR) amyloid (ATTR) amyloidosis." (PMID 33367948, 2021). "These ATTRm amyloidoses are caused by more than 130 different known TTR variants." (PMID 35008816, 2021). "Excess production and accumulation of TTR causes hereditary transthyretin‐mediated amyloidosis." (PMID 34529830, 2021). "Diagnoses of amyloidosis were limited (2 of 157 patients), although related heart disease diagnoses, including cardiomyopathy and heart failure, were significantly increased in individuals with P/LP TTR variants who were aged >60 years." (PMID 34746851, 2021). "In addition, previous studies found that the accumulation or mutations of transthyretin was associated with amyloid diseases such as senile familial amyloid polyneuropathy, systemic amyloidosis, and familial amyloid cardiomyopathy." (PMID 34500744, 2021). "For example, glycosylation has been implicated in TTR amyloidosis." (PMID 33203794, 2020). "In these amyloidoses, dozens of proteins or protein components of disease-associated amyloid deposits have been identified so far, for instance, amyloid-beta peptide, alpha-synuclein, Huntingtin and transthyretin." (PMID 32709875, 2020). "In a translational setting of a murine model, they could knock down transthyretin (TTR) in the liver, where TTR mutations cause transthyretin amyloidosis." (PMID 39698114, 2020). "Patisiran was applied for treatment of TTR mediated amyloidosis which could reduce the expression of target protein mutated transthyretin (TTR) to 80% at the dose of 0.3 mg/kg every 3 weeks." (PMID 33716725, 2020). "In hereditary TTR-mediated amyloidosis (hATTR amyloidosis), pathogenic mutations in the TTR gene cause abnormal amyloid proteins to accumulate in tissues including nerves, heart, and gastrointestinal tract, resulting in a multisystem disease with a heterogeneous clinical presentation." (PMID 32062791, 2020). "If glycosylation is a factor in tagging TTR monomers for rapid proteolytic degradation, decreased glycosylation activity could result in a sufficient buildup of monomer to cause development of amyloidosis." (PMID 33203794, 2020). "TTR protein contains β strands that become folded due to single point mutations in the TTR gene and which results in deposits of insoluble TTR protein, causing amyloidosis." (PMID 32580326, 2020).
amyloidosis (continued). "Any variable which may change TTR conformational distributions and stabilities would change the predicted risk of amyloidosis." (PMID 33203794, 2020). "In addition to study Fx-005, a parallel study was conducted in patients with amyloidosis due to non-V3OM TTR mutations (excluding V122I) to assess effects of tafamidis on TTR stabilization and clinical outcomes." (PMID 31407119, 2019). "Further analyses of other mutant forms of TTR will provide additional insights into distinct misfolding pathways of TTR variants that may cause tissue-selective TTR amyloidosis." (PMID 30631096, 2019). "Human transthyretin (TTR) is implicated in several fatal forms of amyloidosis." (PMID 30804345, 2019). "Two distinct siRNA-SNAPL formulations, the ALN-TTR01 and ALN-TTR02, targeting the TransThyRetin (TTR, TRANsports THYroxine and Retinol) gene encoding for the protein TransThyRetin (TTR), were developed by Alnylam Pharmaceuticals for the cure of amyloid diseases associated with a TTR overexpression." (PMID 31344836, 2019). "Amyloid formation by any of the ca. 100 different variants of TTR so far described leads to early-onset TTR amyloidosis with autosomal dominant inheritance, such as familial amyloid cardiomyopathy (FAC), familial amyloid polyneuropathy (FAP), and leptomeningeal amyloidosis." (PMID 31358790, 2019). "We have studied the intrinsic fluorescence spectra of a monomeric variant of human transthyretin (M-TTR), a protein involved in the transport of the thyroid hormone and retinol and associated with various forms of amyloidosis, extending our analysis to the second order derivative of the spectra." (PMID 31358790, 2019). "This reduces the amyloid accumulations which are linked to transthyretin-mediated amyloidosis." (PMID 31608113, 2019). "In this context, lipid-encapsulated nanoparticles containing double-stranded small interfering RNA (siRNA) have been applied for binding to transthyretin (TTR) mRNA causing degradation of TTR deposits present in patients with hereditary TTR-mediated amyloidosis." (PMID 30551668, 2018). "NPA = Positive tests for at least one mutation of Amyloidosis by TTR mutation (n = 111)." (PMID 29970125, 2018). "ATTR amyloidosis was diagnosed based on the clinical findings, heterozygosity for the new TTR mutation, amyloid deposition in salivary glands and gastric tissue, and confirmation of the presence of the p.Gly87Arg variant within the deposits by tandem mass spectrometry-based proteomic analysis." (PMID 28802308, 2017). "However, OLT is only recommended for patients with early-stage hATTR amyloidosis, and survival varies according to modified body mass index (mBMI), disease duration/severity, and TTR mutation." (PMID 28893208, 2017). "Human TTR and a number of its mutant forms have been associated with amyloid diseases." (PMID 29240759, 2017). "The APOLLO study examines the efficacy and safety of the investigational RNAi therapeutic patisiran in a broad hATTR amyloidosis population, including patients with any amyloidogenic TTR mutation and with a wide range of neuropathy severity and age at baseline." (PMID 28893208, 2017). "TTR amyloid diseases are associated with four protein aggregation ‘gain of toxic function diseases’, which are senile systemic amyloidosis (SSA), familial amyloidotic polyneuropathy (FAP), familial amyloidotic cardiomyopathy (FAC), and familial leptomeningeal amyloidosis." (PMID 26108284, 2015). "The molecular mechanism of this remarkable phenomenon and whether it underlies amyloid fibrillogenesis by other amyloidogenic TTR variants, including the wild-type protein, are fundamental to understanding the pathogenesis of this amyloid disease." (PMID 26286619, 2015). "Although evidence for cytotoxicity in systemic amyloidosis remains less well characterized, toxic oligomeric species of transthyretin have recently been identified, which presumably underlie the neuropathy seen in patients with transthyretin-associated amyloidosis." (PMID 26393799, 2015).